RACGAP1P1 (Rac GTPase activating protein 1 pseudogene 1)
Synonyms: FKSG42; formerly RACGAP1P
Gene: Processed pseudogene on chromosome 12 (45,063,473 to 45,065,351, reverse strand). Ensembl gene ENSG00000257331.
Diseases named in the same sentence as RACGAP1P1 in open-access papers:
RACGAP1P1 is named in the same sentence as 6 diseases in open-access papers, as found by Europe PMC text mining. Sharing a sentence is not in itself a finding about the gene and the disease.
RACGAP1P1 shares sentences with these, for which no sentence is quoted: breast carcinoma (5 papers); tumor (4); hepatocellular carcinoma (3); cancer (2); liver cancer (1); lymph node metastasis (1).